NEO1 (neogenin 1)
Diseases named in the same sentence as NEO1 in open-access papers (continued):
Sharing a sentence is not in itself a finding about the gene and the disease.
NEO1 also shares sentences with these, for which no sentence is quoted: glioblastoma (2 papers); neurodegenerative disease (2); acute leukemia (1); basal cell carcinoma (1); Becker muscular dystrophy (1); Bladder cancer (1); cecum adenocarcinoma (1); colon adenocarcinoma (1); colon mucinous adenocarcinoma (1); dental caries (1); embryonal carcinoma (1); hematologic malignancies (1); kidney cancer (1); leukemia (1); lymphoma (1); Myeloma (1); neurological diseases (1); normal pressure hydrocephalus (1); periodontitis (1); prostate tumors (1); renal cell carcinoma (1); rheumatoid arthritis (1); subarachnoid hemorrhage (1); substance dependence (1); systemic lupus erythematosus (1).